IFNG (interferon gamma)
Diseases named in the same sentence as IFNG in open-access papers (continued):
Sharing a sentence is not in itself a finding about the gene and the disease.
breast cancer (continued). "So far IL-2, IFNα, IFNβ and occasionally IFNγ, IL-6, IL-12 have been the cytokines used for anti-tumor treatment of advanced breast cancer either to induce or increase hormone sensitivity and/or to stimulate cellular immunity." (PMID 32887217, 2020). "Remarkably, breast cancer patients with a low monocyte IFNγ response were significantly more likely to relapse." (PMID 33042791, 2020). "In this study, a panel of four phenotypically diverse human breast cancer lines were exposed in vitro to the combination of Th1 cytokines Interferon-gamma (IFN-γ) and Tumor Necrosis Factor-alpha (TNF-α) and lipophilic statins." (PMID 32041347, 2020). "The top target differentiating the Aldh1l2 KO group from the WT/Aldh1l1 KO group is interferon gamma, which would be in agreement with recent findings that interferon signaling is responsive to folate status in murine mammary cancer cells." (PMID 33168096, 2020). "We have shown that ALIX is a negative regulator of EGFR activity, that its depletion significantly augments IFNγ-induced PD-L1 surface expression in human breast cancer cells, and that this upregulation is EGFR activity dependent." (PMID 30021161, 2018). "For this, we used the well-characterized and established syngeneic BALB/c mouse model with the 67NR breast cancer cell line, which demonstrates robust induction of PD-L1 in response to IFNγ." (PMID 30021161, 2018). "GRP78 heterozygousity also affected IFNγ-stimulated CD11b+ cell-mediated 4T1B breast cancer cell clearance as measured by electrical impedance, providing further evidence that GRP78 modulates macrophage function." (PMID 29113324, 2017). "First, breast cancer cells, in part via IFNγ, induce IDO1 expression in endothelial cells, leading to tryptophan degradation." (PMID 29156701, 2017). "Recent studies suggested that IFNγ can induce an overexpression of IDO1 in varieties types of tumours including breast cancer, followed by a breakdown of tryptophan." (PMID 29156701, 2017). "In term of breast cancer, up to 30% of those diagnosed as in situ breast cancer exhibit tumour dormancy with metastasis-free, which will make these individuals particularly vulnerable to any adverse activities of IFNγ-related breast cancer management." (PMID 29156701, 2017). "In contrast, inhibition of pY239/240ShcA-coupled signalling pathways in mammary tumours (MT/Shc2F/2F) specifically elicits immune surveillance in vivo, despite the fact that IFNγ-driven signalling responses are basally reduced in these cell lines in vitro." (PMID 28276425, 2017). "To eliminate the potential pleiotropic effects of IFNγ pre-treatment in the trans-suppression co-culture assay, we used the human breast cancer cell line MDA-MB-231BR, which has a high PDL1 basal cell surface expression level." (PMID 28325288, 2017). "The strength of association between PDL1 expression and the probability of activation of immune-related pathways (IFNα, IFNγ) was also much lower in pancreatic carcinomas than in breast cancers and GISTs." (PMID 27589570, 2016). "T cells from the breast cancer patients showed IFNγ production in ELISpot analysis, similar to levels observed in normal donors." (PMID 27367740, 2016). "Inflammatory cytokines including interleukins (IL-1β, IL-2, IL-6, IL-8, IL-12), tumor necrosis factor alpha (TNF-α), and interferon gamma (IFN-γ) are key inflammatory mediators of interest in breast cancer progression." (PMID 26970739, 2016). "Since breast cancer cell lines are only composed of epithelial cells, the effect of IFNγ produced by lymphocytes for the induction of HLA gene expression can be excluded, which in turn, emphasizes the importance of autonomous IFN signaling in tumor cells." (PMID 27121061, 2016). "Based on RNA-Seq data from TCGA, expression of IP genes showed a strong correlation with expression of IFNG and T-cell genes in breast cancer." (PMID 27659694, 2016).
breast cancer (continued). "IFNγ is a known inducer of PD-L1 expression in various cell types, including mammary carcinoma cells and is often present in the tumor microenvironment." (PMID 26859684, 2016). "The expression of interferon γ (IFNγ) in tumors improves tumor specific T cell recruitment and mediates the apoptosis of breast cancer cells via down-regulation of anti-apoptosis Bcl-2 family members and inducing growth arrest at mid-G1." (PMID 26313265, 2015). "Ad-MGBA-CD8+CTLs displayed the highest level of IFNγ during killing of MDA-MB-415 cells when compared with the other four CD8+CTL populations or when compared with the other two breast cancer cell lines." (PMID 23650543, 2013). "PD-L1 was alsodecreased in IFNγ-treated COX-2KD mouse mammary cancer cells in vitroand, compared to control cells, growth of COX-2KD cells as orthotopic tumorsin immune competent mice was markedly suppressed." (PMID 24004819, 2013). "Using the ELISPOT assay, we also detected IFNγ secretion in different CD8+CTLs when stimulated with three different breast cancer cell lines." (PMID 23650543, 2013). "In breast cancer cell lines, IFNγ down-regulates S100A7 expression, through STAT1 transcriptional activity." (PMID 23285311, 2012). "IFNα, IFNβ, and IFNγ have each been used in the treatment of breast cancer either to induce antiestrogen sensitivity and/or stimulate cellular immunity." (PMID 22295238, 2011). "In ER- breast cancer, IL12, IL2 and IFNG were significantly associated with good prognosis, while TGFB and EGFR pathway activation were associated with poor clinical outcome." (PMID 21050467, 2010). "Rentzsch and colleagues found that PBMCs from one out of ten primary breast cancer patients exposed to SSX2-p103–111 significantly increased their mRNA expression of IFNγ by QT-RTPCR analysis." (PMID 20981248, 2010). "Specifically, IL12, IL2 and IFNG, all involved in Th1 mediated immune response, showed strong correlations in both ER+ and ER- breast cancer, while IL13 (involved in a Th2 immune response) was generally anti-correlated to these pathways." (PMID 21050467, 2010). "In line with this, IFNγ has been shown to regulate p21 in human breast cancer cells via transcriptional upregulation." (PMID 20559421, 2010). "In breast cancer patients with skin metastasis, local injection of IFNγ results in the total or partial regression of the skin lesions." (PMID 17697357, 2007). "In this way, it has been show that IFNγ produce this antitumoral effect up-regulating the expression of p21 and resulting cell cycle arrest in breast cancer cell lines." (PMID 17697357, 2007). "Ruiz-Ruiz and Lopez-Rivas have suggested that, in breast cancer cell lines, IFNγ favors activation of mitochondria-operated apoptotic pathway by TRAIL; this activation can be inhibited in bcl-2 overexpressing cells." (PMID 17697357, 2007). "The aim of this study was to elucidate the expression patterns of IFNγ and its receptors in human benign breast lesions and in in situ and infiltrating breast cancers, and to relate to the proliferation and apoptosis levels found in this tissues." (PMID 17697357, 2007). "The IFNγ ability to inhibit the growth of several tumor cell lines, including breast cancer cells, has been demonstrated in different studies." (PMID 17697357, 2007). "The underlying inflammatory cause for increased sClever-1 is further supported by our data showing the induction of the release by IFNγ/TNFα, the sustained sClever-1 levels after tumor surgery and the different inflammatory cytokine profiles observed in breast cancer patients." (PMID 40756372, 2025). "In breast cancer, PPP2R2B expression was strongly associated with immune check point inhibitor genes such as BZMA, PRF1, and IFNG, suggesting that downregulation of PPP2R2B could take part in tumor immune evasion." (PMID 39851522, 2025).
breast cancer (continued). "We found that SLAMF6 expression was highly correlated not only with the expression of T-cell markers (CD3E, CD8B, CD8A, and CD4) but also with upregulation of TCF7, PDCD1 encoding PD-1, GZMK, and effector-associated genes including IFNG and PRF1 in breast cancer." (PMID 38287061, 2024). "Moreover, doxorubicin upregulates CXCL8 and TNF in lung cancer cells and IL12-induced IFNG in xenografted breast cancer." (PMID 39759512, 2024). "The results showed that the expression of PLK1 and IFNG in human breast cancer cells were significantly higher than in human normal mammary epithelial cells; while the expression of S100B and IRS2 were significantly lower than in human normal mammary epithelial cells." (PMID 39314848, 2024). "Several studies have revealed a link between IFNG and breast cancer." (PMID 37154982, 2023). "Our results suggest that IFNG may be mainly expressed by CD8+ T cells in the breast cancer tumor microenvironment." (PMID 37154982, 2023). "The correlation analysis of TCGA-BRCA (breast cancer) revealed several inflammatory pathways associated with increased tumor NOS2/COX2 expression that influenced clinical outcomes, including the antitumor-associated IFNγ, TNFα, IL2, IL1, and IL17 pathways." (PMID 37169743, 2023). "The signature gene IFNG is positively related to CD8+ T cell infiltration in breast cancer." (PMID 37154982, 2023). "As the inhibitors of PD-L1, which is encoded by the CD274 gene, are already in clinical use and the gene product of CD70 is another potentially interesting immunotherapy target, we focused on the CD274:CD70 interaction in the context of IFNγ expression in breast cancer." (PMID 37106127, 2023). "Therefore, we tried inducing SLFN11 expression using in-vitro Interferon Gamma stimulation in our breast cancer cells." (PMID 38001424, 2023). "Furthermore, the association between high levels of the IFNγ MCP and favorable outcomes was found in a cross-TCGA analysis and within individual indications, such as sarcoma, breast cancer, or bladder cancer." (PMID 37543621, 2023). "Therefore, the results in TCGA cohort demonstrated that GZMA, GZMB, and IFNG in the low-risk group were highly expressed, while TGFB1 was elevated in high-risk breast cancer patients (p < 0.001)." (PMID 35619902, 2022). "The anti-CD137 agonist urelumab can overcome transforming growth factor (TGF)-β-mediated inhibition of human NK-cell proliferation and anti-tumor function and preserve the expressions of NKG2D, granzyme B, and interferon-gamma (IFN-γ) in HER2-positive primary breast cancer." (PMID 36601109, 2022). "IFNγ-induced ISG15 might affect the response of breast cancer cells to endocrine therapy with fulvestrant or tamoxifen." (PMID 36319753, 2022). "In our mouse model of 4T1 breast cancer, PB manifests the same artifact (tumor-induced T cell suppression) when assessing IFNγ+ CD8+ T cells by ICS, while such an “immunosuppression” was not concluded using the IFNγ-eYFP reporter mice by living cell immunostaining and flow cytometric analysis." (PMID 35126389, 2022). "GBP2 is an IFNγ-induced GTPase involved in protective immunity against microorganisms and is also a marker for an efficient T cell response in breast carcinomas." (PMID 36055241, 2022). "Combined with the observation that IFNγ stimulation does not increase ROS levels, these data further support the hypothesis that IFNγ likely perturbs the ROS-scavenging potential of breast cancer cells." (PMID 34083537, 2021). "Thus, IFNγ sensitizes multiple breast cancer cell lines, spanning distinct molecular subtypes, to phenformin in a STAT1-dependent manner." (PMID 34083537, 2021). "Furthermore, HDAC2 knockout reduced IFNγ-induced PD-L1 expression, lymphocyte infiltration, and retarded tumor growth and metastasis in the breast cancer mouse models." (PMID 34365463, 2021). "Moreover, steady-state levels of amino acid constituents of glutathione (Glu, Cys, and Gly) are unaffected by IFNγ in MT4788 breast cancer cells." (PMID 34083537, 2021).
breast cancer (continued). "Intratumoral administration of viral vectors expressing IFNg represents a promising strategy for immunomodulation of the TME, especially for locally advanced tumors (breast cancer, prostate cancer), which allows i.t. administration to avoid the systemic toxicity of IFNg." (PMID 34835178, 2021). "Treating the patient with interferon gamma could encourage metastatic breast cancer cells to re-activate a silenced or dampened JAK-STAT signaling, while at the same time mitigating the overexpression of the alternative (adaptive) phenotype." (PMID 34568068, 2021). "Moreover, IFNγ stimulation enhances phenformin-induced α-ketoglutarate (αKG) levels as well as the αKG/citrate ratio in breast cancer cells." (PMID 34083537, 2021). "Moreover, IFNγ modestly decreased the metabolic flexibility of MT4788 breast cancer cells in a STAT1-dependent manner." (PMID 34083537, 2021). "We first assessed whether IFNγ or phenformin, alone and in combination, altered glutathione levels in breast cancer cells." (PMID 34083537, 2021). "We next assessed whether IFNγ altered the metabolic flexibility of breast cancer cells in response to phenformin treatment." (PMID 34083537, 2021). "The suite of peptides displayed under conditions of IFNγ treatment included many known tumor associated antigens, with the HLA-II repertoire sampling 17 breast cancer associated antigens absent from those sampled by HLA-I molecules." (PMID 33968037, 2021). "Interestingly, our previous report provided evidence that the function of the CD8+ IFNγ-producing T cell subset in murine mammary carcinoma was strongly hampered by intravenous iron supplementation." (PMID 34108960, 2021). "Moreover, it was also found to be significantly up‐regulated in basal-like breast cancer subtype than the other subtypes and showed better survival prognosis as it is involved in interferon-gamma response and PD‐L1 positivity." (PMID 33304345, 2020). "In addition, classical monocytes from lymphoma and breast cancer patients showed reduced responsiveness to IFNγ as indicated by the lower levels of STAT1 phosphorylation following stimulation." (PMID 33042791, 2020). "Downregulation of IL-17C and its downstream cytokine IFNγ in breast cancer with a high level of ER expression indicates that IL-17C signaling transduction may also be associated with the regulation of ER." (PMID 33102239, 2020). "Moreover, the M1 high basal-like breast cancer group showed a higher expression of interferon-gamma induced chemokines and guanylate-binding proteins (GBPs) involved in immunity against microbes." (PMID 33304345, 2020). "In addition to those genes that encode downstream products of IL-17A/IL-17F signaling transduction, the expression levels of IFNG, FOS, FOSB1, and FOSL1 were also found to be associated with ER status in breast cancer." (PMID 33102239, 2020). "In an earlier murine mammary carcinoma transplantation model study, it was disclosed that interferon gamma-induced human GBP1 could inhibit the tumor growth, although the recent studies indicated its role of oncogene in breast cancer." (PMID 31998647, 2019). "The comparison between three PDL1 signatures revealed a stronger cytotoxic profile correlated with anti-tumor pathways activation (IFNα and IFNγ) in breast cancers and GISTs, suggesting a sustained activation of anti-tumor T-cells in breast cancers and GISTs of good prognosis." (PMID 27589570, 2016). "Therefore, the TNFAIP1/POLDIP2 SFGM is also potentially regulated by STAT1 and Sp1 as well as stimulated by interferon-gamma in breast cancer cells." (PMID 20158880, 2010). "The aim of this study was to investigate the expression patterns of IFNγ and its two receptors (IFNγ-Rα and IFNγ-Rβ) by Western blot and immunohistochemistry, in order to elucidate its role in the different types of human breast cancer (in situ and infiltrative)." (PMID 17697357, 2007).
breast cancer (continued). "IFNγ might be unable to activate p21 to stop the cell cycle, suggesting a possible participation in breast cancer development." (PMID 17697357, 2007). "In breast cancer cell lines, IFNγ treatment produces an increase in p21." (PMID 17697357, 2007). "Perhaps, IFNγ might be unable to activate p21 to stop the cell cycle, suggesting a possible participation in breast cancer development." (PMID 17697357, 2007). "In different mammary carcinoma cell lines IFNγ induces growth arrest at mid-G1." (PMID 17697357, 2007). "An additional role for the constitutively elevated CIS may be to decrease breast cancer sensitivity to interferons, similar to the decreased sensitivity to IFNγ seen in cutaneous T-lymphoma (CTCL) cell lines that constitutively express SOCS-3." (PMID 12888825, 2003). "Furthermore, Treg accumulation in breast cancer patients down-regulates effector T cell proliferation and pro-inflammatory factors such as IFNγ, thus systematically altering the immune response toward an anti-inflammatory, pro-tumorigenic phenotype facilitating tumor metastasis." (PMID 38038865, 2023). "However, uptake of LDL-C led to impaired IFNγ production and reduced breast cancer cell death." (PMID 34552769, 2021). "One subtype in the breast tumour that was IFNγ-positive had no obvious similarity to any of the subtypes observed in the blood γδ T cell and was the only subtype associated with improved overall survival of breast cancer patients." (PMID 33268347, 2021). "Previous studies have suggested that effector T cell-derived IFNγ contributes to high levels of PD-1 expression in the tumor microenvironment; CCL2 attracts monocytes, increases the number of tumor-associated macrophages and promotes angiogenesis in breast cancer." (PMID 33102239, 2020). "Also in H3396 breast cancer cell lysates the pT/S antibody could immunoprecipitate endogenous human IRF1 induced by IFNγ treatment." (PMID 30854564, 2019). "Moreover, the combination of VEGFR-2 and PD-L1 antibodies induces high endothelial venules (HEVs) to facilitate IFNγ+ CD4+ and IFNγ+ CD8+ lymphocyte infiltration in breast cancer and pancreatic neuroendocrine tumors, finally leading to tumor cell apoptosis and necrosis." (PMID 31835465, 2019). "Additionally, NK cells interacting with galectin-9 on the breast cancer cell surface may release interferon gamma (IFN-γ) in response which could activate cytotoxic lymphoid cells located in the area of the tumor microenvironment." (PMID 31354733, 2019). "IFNγ could be a potential therapeutic tool in breast cancer." (PMID 17697357, 2007). "Therefore, present observations could suggest that IFNγ could be a potential therapeutic tool in breast cancer." (PMID 17697357, 2007). "Interestingly, there is evidence that mammary carcinoma lines are resistant to the growth inhibitory actions of IFNγ, which could be the result of constitutive expression of SOCS proteins." (PMID 12888825, 2003). "Conversely, in breast cancer, mast cells recruited and activated by tumor cells can induce transcriptional changes in genes such as SPP1, PDCD1, IL17A, TGFB1, KITLG, and IFNG, leading to anti-tumor effects." (PMID 40495762, 2025). "In estrogen receptor-positive breast cancer (ER+ BC, of any stage) patients, we found that ~40% harbor defects in immune signaling at the time of diagnosis, including altered signaling responses to IL-6, IFNγ, TGFβ, IL-10, and IL-4 in various immune cells." (PMID 39389979, 2024). "PLK1, IFNG, S100B, and IRS2 were expressed at significantly different levels between breast cancer and normal breast tissues." (PMID 39314848, 2024). "Another study on breast cancer cells also showed that IRF1, as part of the IFNγ and TNF-α signaling pathways, plays a role in suppressing growth and inducing apoptosis of malignant cells." (PMID 38396830, 2024).